TNF (tumor necrosis factor)
Diseases named in the same sentence as TNF in open-access papers (continued):
Sharing a sentence is not in itself a finding about the gene and the disease.
Parkinson disease (continued). "Similarly, ACS84 outperforms NaHS in inhibiting lipid peroxidation, MAO-B, and mitochondrial dysfunction in Parkinson’s disease, stimulating Nrf2 and suppressing NO, TNF-α, and p38/JNK-MAPK in Aβ-induced microglia." (PMID 41465271, 2025). "Further, specific inflammatory responses were observed with microglial activation and increased expression of pro-inflammatory cytokines (like IL-6, TNF-α), specifying role for TiO2 NPs in neuroinflammation - a key driver in diseases like Alzheimer’s and Parkinson’s." (PMID 41409624, 2025). "Similarly, citronellol demonstrated suppression of TNF-α, IL-1β, and IL-6 in a Parkinson’s disease model, indicating a direct action in disrupting the NF-κB-mediated inflammatory cascade." (PMID 40656940, 2025). "Together with caspase-1, these mechanisms generate the inflammasome NLRP3, which triggers the release of proinflammatory IL-1β; other proinflammatory proteins, like as TNFα and iNOS, that are generated by M1 cells also have a role in neurodegeneration in Parkinson’s disease." (PMID 40650193, 2025). "Furthermore, the substantia nigra (SN) and cerebrospinal fluid [CSF] of post-mortem Parkinson’s disease have been shown to have elevated TNF-α than the healthy adult brain." (PMID 39910608, 2025). "Also, regular HIIT has been shown to reduce TNF-α levels and slow down the progression of Parkinson’s disease by improving serum antioxidant capacity." (PMID 38626052, 2024). "The study hypothesized that SHE possesses antioxidants that could mitigate Parkinson’s symptoms by influencing α-synuclein, acetylcholinesterase (AChE), TNF-α, and IL-1β." (PMID 38551975, 2024). "Collectively, Atsttrin could be considered a therapeutic agent in the therapy of Parkinson’s disease via targeting TNFα and in this case could be a future novel drug candidate for the treatment of neurodegenerative diseases." (PMID 38642286, 2024). "Studies have shown that patients with Parkinson’s disease with H. pylori infection exhibit higher levels of pro-inflammatory cytokines, such as TNF-α and IL-6, which may contribute to disease progression." (PMID 39202269, 2024). "IgG from peripheral blood of Parkinson’s patients triggers TNF-alpha release in mouse microglia." (PMID 38904783, 2024). "Recently, it has been shown that activation of microglia leads to the conversion of normal astrocytes to reactive astrocytes via secretion of IL‐1α, TNF‐α and complement component 1 (C1q) (T/I/C) in a variety of neurodegenerative diseases including AD and Parkinson's disease." (PMID 37905690, 2024). "TNF (Tumor Necrosis Factor)-α elevated inflammatory factor expression induced hippocampal neuron downregulation while accelerating the degradation of myosin light chain 2-activated caspase-3 activation and apoptosis in Alzheimer’s and Parkinson’s disease." (PMID 37691828, 2023). "Anti-TNFα therapy protects dopaminergic neurons and reduces the incidence of Parkinson’s disease." (PMID 35250991, 2022). "Furthermore, it was reported to protect dopaminergic neurons in rats with experimentally induced parkinsonism TNF-α production suppression." (PMID 35893792, 2022). "Additionally, the miR-3473b targets the triggering receptor expressed on myeloid cells 2 (TREM2) and Unc-51 like autophagy activating kinase 1 (ULK1) to regulate the inflammatory response, such as the secretion of TNF-α and IL-1β, in Parkinson's disease." (PMID 36572876, 2022). "Furthermore, as with the prodromal phenotype of Parkinson's disease, the neurodegenerative process of iRBD is mediated by TNF-α similarly, suggesting that a-synuclein pathologies have already existed in iRBD and play a role in the activation of microglia." (PMID 35250828, 2022). "TNF-α is believed to be involved in a variety of inflammatory diseases, including neurodegenerative diseases, such as Alzheimer’s disease (AD) and Parkinson’s disease (PD), cancer, and diabetes." (PMID 36158549, 2022).
Parkinson disease (continued). "SIRT6 and SIRT7 regulate TNFα, and reduced activity leads to Parkinson’s disease." (PMID 33668997, 2021). "In agreement with previous studies, our study showed that the toxin MPTP induces phenotypes associated with Parkinson’s disease in mice such as decreased levels of dopamine and GSH; increased levels of MDA, iNOS, and TNF-α; and increased numbers of GFAP positive astrocytes." (PMID 33796021, 2021). "The pathological features of these patients overlap with those of Alzheimer’s disease (AD) and Parkinson’s disease (PD) and are presumably caused by direct neural damage and long-term production of proinflammatory cytokines (e.g., IFN-γ, TNFα, Il-1β) secreted by WNV specific T cells." (PMID 34440903, 2021). "The correlation between Bacteroidetes and plasma TNF-α levels, as well as between Verrucomicrobia and plasma IFN-γ levels, reflect the association between Parkinson's disease and the systemic inflammatory response, as well as the interaction between the disease and altered intestinal flora." (PMID 32318067, 2020). "Since microglial cells respond to peripheral inflammatory signals by producing more inflammatory molecules such as TNFα, we evaluated the morphology of these in substantia nigra and striatum, the two main areas that show dopamine depletion in Parkinson's disease." (PMID 32015787, 2020). "The role of TNFα in neurodegeneration has been widely reported, not only in the retina but also in neurodegenerative diseases such as Alzheimer's or Parkinson's." (PMID 31680831, 2019). "Moreover, βHB can also suppress mRNA expression of the inflammatory cytokines TNF-α, IL-1β, and IL-6 in the microglia of a rat model of lipopolysaccharide-induced Parkinson’s disease." (PMID 29443873, 2018). "In addition, a significant increase in immunoreactive TNF-α in glial cells has been reported in the substantia nigra of Parkinson's disease (PD) patients compared to the control group." (PMID 29973883, 2018). "One such critical role in neuroinflammation has been illustrated whereby TNF-α can damage dopaminergic neurons and thus anti-TNF agents may ameliorate Parkinson’s disease." (PMID 26901230, 2016). "Here we review the interrelation of oxidative stress and inflammation in the two major chronic neurodegenerative diseases, Alzheimer's and Parkinson's disease, and discuss the dual role of TNF in promoting neurodegeneration and tissue regeneration via its two receptors." (PMID 25834699, 2015). "Furthermore, PYC shows neuroprotective effects through antioxidant and anti-inflammatory potency, in traumatic brain injury and Parkinsonism mouse models and inhibited the upregulation of TNF-α, IL-6 and IL-1β." (PMID 26367267, 2015). "Indeed, there are biological gradients between circulating inflammatory markers (cortisol, tumor necrosis factor-α) and objective measures of parkinsonism (gait, sway, psychomotor response)." (PMID 20633189, 2010). "The research hypothesizes that CTE can modulate key biomarkers involved in Parkinson’s pathology, including α-synuclein, interleukin-1β (IL-1β), and tumor necrosis factor-α (TNF-α), assessed through qRT-PCR, as well as interleukin-6 (IL-6) and TNF-α, evaluated through ELISA." (PMID 39642134, 2024). "Thus, TNF-mediated changes inbrain metabolic fluxes could contribute to the pathophysiology ofdiseases like Alzheimer’s, Parkinson’s, and multiplesclerosis, where neuroinflammation is a key feature." (PMID 38943617, 2024). "Acupuncture treatment in Parkinson’s disease (PD) mice significantly reduces the levels of Bacteroides, which previous studies have shown to secrete pro-inflammatory neurotoxins and stimulate macrophages and monocytes to release TNF-α via a polysaccharide-mediated pathway." (PMID 39764388, 2024).
Parkinson disease (continued). "Several studies have confirmed that abnormal IL-6, CRP, TNF-α, IL-4, IL-8, and TGF-β levels were associated with worse motor function assessed by the Unified Parkinson’s Disease Rating Scale (UPDRS), whereas CRP and fractalkine might be potential markers of freezing of gait (FOG)." (PMID 36739284, 2023). "In conclusion, our study investigated biomarkers of phenoconversion in Parkinson's disease and iRBD, as well as the relationship between inflammatory factor TNF-α and orexinergic system in clinical aspect, which might be useful for risk stratification of disease conversion." (PMID 35250828, 2022). "In murine models of neurodegenerative Parkinson’s disease, the intrathecal graft of hDPSCs ameliorated behavioral deficits and dopaminergic (DA) neuron loss, by upregulating anti-inflammatory cytokines IL2, IL4, and TNF-β and reducing IL-1α, IL- 1β, IL6, IL8, and TNF-α pro-inflammatory ones." (PMID 33805573, 2021). "However, the pro-inflammatory tumor necrosis factor (TNF) is known to be toxic to catecholaminergic cells (see Parkinson disease), and this may prevent anti-inflammatory effects in inflamed tissue." (PMID 29941879, 2018). "Similarly in an MPTP mouse model of Parkinson’s disease, knocking out TNF-α significantly reduced microglial activation as measured by cell number and morphology compared to wild-type controls, suggesting the important role played by TNF-α in microglial activation." (PMID 25182840, 2014). "Significantly elevated levels of TNF mRNA and protein can be detected in the rodent midbrain substantia nigra within hours of in vivo administration of two neurotoxins widely used to model parkinsonism in rodents, 6-hydroxydopamine (6-OHDA) and 1-methyl-4-phenyl-1,2,3,6-tetrahydropyridine (MPTP)." (PMID 19917131, 2009). "In a Parkinson’s model, FTY720-NPs injections reducedMPO and NOS activity, downregulated IL-6 and TNFα, and shiftedmicroglia from M1 to M2 phenotype." (PMID 39965088, 2025). "Our findings align with previous studies illustrating the presence of disruptive ionic shuttles in hemorrhagic shock and TNF-mediated MAS disruption and mitochondrial dysfunction in enteric neurons derived from patients with Parkinson’s disease." (PMID 41132685, 2025). "H. pylori infection induces the secretion of pro-inflammatory cytokines, such as TNF-α and IL-6, which can cross a compromised BBB and contribute to dopaminergic neuronal death, promoting parkinsonism." (PMID 39202269, 2024). "The levels of tumor necrosis factor-α and IL-β (including IL6) are significantly increased in Parkinson’s disease, a neurodegenerative disease." (PMID 38892402, 2024). "Previous studies confirmed that baclofen reduced TNF-α and IL-1β expression in the MPTP-induced Parkinson’s disease rat model." (PMID 37903976, 2023). "Immunomodulatory effects on the increased levels of pro-inflammatory cytokines (e.g., TNF-α, IL-1β, and IFN-γ) have been observed in the Parkinson’s patient brains with a large number of proliferating activated immune cells." (PMID 37833807, 2023). "In a mouse model of Parkinson’s disease, EGCG treatment can effectively reduce the expression of serum inflammatory factors including TNF-α and IL-6." (PMID 35409364, 2022). "TNF-α secreted by glial cells generally perpetuates neuroinflammation, and IFN-γ activates glial cells and is increased in Parkinson’s disease." (PMID 35293780, 2022). "The Nrf2 pathway regulates the expression of inflammatory biomarkers inducible NO synthase, interleukin 6 (IL-6), tumor necrosis factor-alpha (TNF-α), as well as the microglial function and neuroinflammation as in cases of Parkinson’s disease." (PMID 35694174, 2022). "CUR also decreased pro-inflammatory cytokines (IL-6, IL-1, and TNFα) in the 1-methyl-4-phenyl-1,2,3,6-tetrahydropyridine (MPTP) model of Parkinson’s disease (PD) and protected dopaminergic neurons from degeneration." (PMID 35216083, 2022).
Parkinson disease (continued). "Inflammation in the brain contributes to the development of Alzheimer’s and Parkinson’s diseases, and pathological studies have shown that increased levels of COX-2, PGE2, IL-6, and TNF-α play a role in these degenerative brain diseases." (PMID 35054942, 2022). "Tanshinone I inhibited NO, IL-6, IL-β, NF-KB, TNF-α, and iNOS mRNA, GCSF production in murine BV-2 microglial cells exposed to LPS of in vitro Parkinson’s disease model." (PMID 34054540, 2021). "We evaluated HiTmIR using miR-34a-5p, for which TNF- and TGFB-signaling, and Parkinson's Disease (PD)-related categories were identified and repeated the pipeline for miR-7-5p." (PMID 33305319, 2021). "Fecal microbiota transplantation (FMT) protects Parkinson's disease model mice by inhibiting neuroinflammation and reducing Toll-like receptor 4/Tumor necrosis factor-alpha (TLR4/TNF-α) signaling." (PMID 34589510, 2021). "It is also worth noticing that chlorogenic acid attenuated the extensive release of release of TNF-α and IL-1β in the substantia nigra of the LPS-injected mice suggesting that this compound may suppress inflammatory response or damage in neurodegenerative diseases including Parkinson’s disease." (PMID 33374338, 2020). "There are a set of pro-inflammatory cytokines including IL-6, TNF, IL-1β, and IFN-γ in the serum of patients with Parkinson's disease." (PMID 32983119, 2020). "Numerous authors have reported that the serum and CSF of Parkinson’s disease patients contain elevated levels of activated CD4 and CD8 T cells and IL-1β, TNF-α, and IL-2." (PMID 25856766, 2015). "Plenty of cytokines such as tumor-necrosis factor-α (TNF-α), interleukin 1β (IL-1β) and IL-6, and the quantities of ROS have been postulated to be involved in the etiology of Parkinson's disease." (PMID 24955210, 2014). "Chronic Parkinsonian monkeys maintain elevated amounts of both cytokines, TNF-α and IFN-γ, during years, and the amounts correlate positively with the degree of Parkinsonism, as well as the level of neuronal degeneration." (PMID 24278772, 2013). "More recently, tumor necrosis factor (TNF) and interleukin-1-beta (IL-1β) signaling pathways have been found to play a role in the pathogenesis of Alzheimer's and Parkinson's diseases." (PMID 22312330, 2012). "TNF-α has been proven to be increased both in the brain and in the cerebrospinal fluid of Parkinsonian patients, and TNF-α is involved in the degenerative processes that occur in Parkinson’s disease." (PMID 40585238, 2025). "Yet, in two recently published α-synuclein-driven parkinsonism models, soluble TNF inhibition did not reduce α-synuclein pathology, neuroinflammation, or dopaminergic neurodegeneration." (PMID 40963744, 2025). "The outcome measures included assessment of Movement Disorder Society Unified Parkinson's Disease Rating Scale (MDS-UPDRS) and serum levels of tumor necrosis factor-alpha (TNF-α), malondialdehyde (MDA), brain-derived neurotrophic factor (BDNF), and α-synuclein (α-Syn)." (PMID 40434674, 2025). "Transplanting beneficial bacteria colonies into Parkinson’s disease mice could protect these mice through inhibiting neuroinflammation and reducing TLR4/TNF-α signaling." (PMID 41195080, 2025). "TNF-alpha had been approved to be increased both in the brain and in the cerebrospinal fluid from parkinsonian patients, and TNF-α is involved in the degenerative processes which occur in Parkinson's disease." (PMID 38948706, 2024). "Moreover, we employed the α-Syn-expressing transgenic Drosophila model of Parkinson’s disease and knocked-down eiger, a TNF superfamily ligand homologue, indicating that the TNF-α pathway plays a role in the common pathogenesis of synucleinopathies." (PMID 36830800, 2023). "Also, in a mouse model of Parkinson's disease, MET reduced the numbers of microglia and proinflammatory cytokines TNF‐α, IL‐1β, IL‐6, and iNOS." (PMID 33443781, 2021).
Parkinson disease (continued). "Based on this data, PFB may play a potentially beneficial role in Alzheimer’s, Parkinson’s, MS and ALS via its reduction of the pro-inflammatory cytokines TNFα, IP-10 and RANTES." (PMID 30401897, 2018). "Other examples include Angiopep, a peptide used to target nanoparticles loaded with therapeutic molecules to brains in e.g., Parkinson’s disease and the tumor homing NRG-peptide fused together with tumor necrosis factor α (TNFα) to induce anti-tumor and toxic reactions towards tumor cells." (PMID 26437400, 2015). "In Parkinsonian primates, unlike other cytokines, TNF-α plays a central role in the long-term inflammatory potentiation of Parkinsonism." (PMID 24278772, 2013). "The literature data has shown that TNFα can exert its neuroprotective effect through TNFR1 receptor, in this case modulating the dopamine transporter (DAT) function, which was observed in animal model of Parkinson’s disease induced through methamphetamine administration." (PMID 38642286, 2024). "Our findings suggest that TNF-α may not have a significant effect on the orexinergic system in patients with Parkinson's disease and iRBD." (PMID 35250828, 2022). "The mRNA expression and protein expression of inflammatory factors (TNF-α, IL-6 and IL-1β) in the substantia nigra were respectively measured by RT-qPCR and ELISA to assess the effect of elevated miR-375 in inflammatory response of 6-OHDA-induced Parkinson’s disease rats." (PMID 31927536, 2020). "However, accumulating evidence shows that Parkinson’s disease is accompanied by immune responses that lead to an increase in serum levels of pro-inflammatory cytokines such as interleukin-6 (IL6), tumor necrosis factor alpha (TNFα), interleukin-1β (IL1B), and interferon gamma (IFNG)." (PMID 32274386, 2020). "TNFα is not the only cytokine that is altered in Parkinson’s disease." (PMID 30071596, 2018). "No cytokine was a specific marker for parkinsonism, but TNF-α, CPP, IL-1β, IL-4, and IL-6 may be useful for early differentiation of atypical parkinsonism to PD." (PMID 30390673, 2018). "Second, although previous studies have reported elevated levels of pro-inflammatory cytokines such as TNF-α, IL-1β, and IL-6 in the CSF of MSA patients compared to those with Parkinson’s disease, we did not detect similar cytokine increases in our mouse model." (PMID 40336104, 2025). "Similarly, in patients with Parkinson’s disease (PD), accumulations of α-synuclein and Lewy body pathology in the substantia nigra pars compacta neurons may in part be a result of elevated SASP-induced cytokines, such as IL-1β, IL-6, and TNFα, generated by senescent astrocytes and other cells." (PMID 33276471, 2020).